FOXL2 (forkhead box L2)
Diseases named in the same sentence as FOXL2 in open-access papers (continued):
Sharing a sentence is not in itself a finding about the gene and the disease.
ovarian tumors (13 papers, 2013 to 2024). "We compared the bulk transcriptomes of hiPSCs, COV434 and KGN ovarian tumor cells, and sorted FOXL2+CD82+ granulosa-like cells from day 5 of a polyclonal differentiation with expression of our previously identified top TFs (NR5A1, TCF21, GATA4, and RUNX1)." (PMID 36803359, 2023). "The CHEK2 c.1100delC mutation was found in a single case of a primary ovarian tumor with the FOXL2p.C134W somatic mutation, morphologically consistent with AGCT and positive by IHC for inhibin, FOXL2, calretinin, and SF1." (PMID 35267514, 2022). "By the age of 15 months, 27% of Runx1 KO mice presented macroscopic ovarian tumors composed of FOXL2+ granulosa cells." (PMID 36430923, 2022). "Conversely, when colon or other extraovarian-primary cancer without FOXL2-positive fibroblasts metastasized to the ovary, there were abundant FOXL2-positive fibroblasts in the secondary ovarian tumors." (PMID 30304016, 2018). "By performing histological and molecular analyses, we demonstrated that the ovarian neoplasms were sex cord-stromal tumors which expressed granulosa cell markers including FOXL2, INHA, and FOXO1." (PMID 29221447, 2017). "In a recent study FOXL2-positive cells were found mainly in primary and secondary ovarian tumors and very few in peritoneal seeding sites suggesting that local tissue environment could be responsible for its omental downregulation." (PMID 31744494, 2019). "All the primary foci of secondary ovarian tumor didn’t contain FOXL2-positive cells." (PMID 30304016, 2018). "To define the molecular characteristics of ovarian tumors in TGFBR1-CAG9Cre mice, we performed immunostaining to examine the expression of a granulosa cell lineage marker FOXL2 and three other granulosa cell-expressed proteins, FOXO1, INHA, and AMH." (PMID 29221447, 2017). "Therefore, although none of the FOXL2 variation carriers in our cohort presented with eyelid malformation or ovarian tumor, the long-term follow-up is still warranted." (PMID 36793102, 2023). "The localization of FOXL2, INHA, FOXO1, AMH, and DDX4 was detected in the granulosa cell or oocyte compartment of control ovaries, while ovarian tumor tissues from TGFBR1-CAG9Cre mice were immunoreactive with FOXL2, INHA, and FOXO1, supporting the development of GCTs in these mice." (PMID 29221447, 2017).
ovarian failure (12 papers, 2008 to 2024). "To date, it remains a great challenge to distinguish BPES types I and II and ovarian dysfunction with varied severity based on different FOXL2 mutations." (PMID 35574016, 2022). "According to clinical examinations, ovarian insufficiency was found in one BPES type I family carrying the FOXL2 variant c.307C > T; p.(Arg103Cys)." (PMID 33796131, 2021). "In addition, high phenotypic variability existed within FOXL2 mutations of the same domain and even within the same mutation, although with the presence of ovarian dysfunction." (PMID 35574016, 2022). "The BPES patients with FOXL2 mutations in our study were infertile due to ovarian dysfunction with variable severity, but none exhibited POI until now." (PMID 35574016, 2022). "However, it is not possible to exclude the involvement of autosomal genes in the onset of ovarian insufficiency as some genes located on autosomes have been associated with the POF phenotype, for example INHA, FSHR and FOXL2." (PMID 22794123, 2012). "In contrast, when incubated with the StAR promoter, a faint band was detected in the mutant FOXL2 [c.223C > T; p.(Leu75Phe), c.293G > A; p.(Trp98Ter), c.307C > T; p.(Arg103Cys), c.383G > A; p.(Trp128Ter), and c.415G > T; p.(Gln139Ter)] group, which may be a predictor of ovarian dysfunction." (PMID 33796131, 2021). "In a study in which a portion of the Foxl2 coding region (amino acids N-61) was fused to the β-galactosidase gene (LacZ), homozygous Foxl2-lacZ mice exhibited ovarian failure resulting from the absence of granulosa cell differentiation at an early stage of follicular development." (PMID 20167115, 2010).
gastric cancer (11 papers, 2015 to 2025). A primary or metastatic malignant neoplasm involving the stomach. "A previous publication reported that FOXL2 directly regulates the EMT process in chemoresistant gastric cancer." (PMID 36846934, 2023). "A previous study discovered that FOXL2 was abnormally high in gastric carcinoma and promoted EMT‐induced metastasis in chem‐resistant gastric cancer." (PMID 36846934, 2023). "For example, miR-937 inhibit cell proliferation and metastasis in gastric cancer cells by downregulating FOXL2." (PMID 35336829, 2022). "A high motility group protein HMGA2 has been revealed to regulate metastases and epithelial-to-mesenchymal transition of chemoresistant gastric cancer by up-regulating Foxl2 expression." (PMID 35053111, 2022). "Furthermore, FOXL2 expression was discovered to be abnormally high in gastric carcinoma and to boost cell proliferation as well as epithelial–mesenchymal transition (EMT)‐induced metastasis in chemoresistant gastric cancer." (PMID 36846934, 2023). "Yu and colleagues found that miR-937 was downregulated and inhibited cell proliferation and metastasis in gastric cancer by targeting FOXL2, which might be a potential target for the treatment of gastric cancer." (PMID 31856857, 2019). "In particular, we reported promoter methylation of FOXL2 in gastric cancer." (PMID 26121593, 2015). "The promoter methylation of FOXL2 may have a significant role in tumorigenesis in gastric cancer." (PMID 26121593, 2015). "FOXL2 participates in the occurrence and development of numerous tumors, such as ovarian GCT27 and chem‐resistant gastric cancer." (PMID 36846934, 2023). "Another research in gastric cancer revealed that HMGA2, FOXL2, and ITGA2 were increased in metastatic lymph nodes and distant metastases in gastric cancer, and suppressing the HMGA2-FOXL2-ITGA2 pathway could serve as a new strategy in further treatment in gastric cancer." (PMID 30428899, 2018).
Blepharophimosis Ptosis Epicanthus Inversus Syndrome (10 papers, 2008 to 2023). "Mutations of the Foxl2 gene in humans are associated with Blepharophimosis Ptosis Epicanthus Inversus Syndrome (BPES)." (PMID 36575161, 2022). "Blepharophimosis-ptosis-epicanthus inversus syndrome (BPES) is a rare autosomal-dominant genetic disorder, and mutations in the forkhead box L2 (FOXL2) gene are one of the major genetic causes." (PMID 34966851, 2021). "The forkhead transcription factor (FOXL2) plays a crucial role in blepharophimosis-ptosis-epicanthus inversus syndrome (BPES), sex determination, ovary growth and development, and cell cycle regulation." (PMID 31221094, 2019). "FOXL2 is the unique classical PIS-regulated gene and encodes for a transcription factor responsible for BPES in heterozygous mutated patients (Blepharophimosis Ptosis Epicanthus inversus Syndrome, MIM#110100)." (PMID 18384673, 2008). "Mutations in FOXL2 have been found to be associated with POI, in the form of BPES type 1." (PMID 33716979, 2021).
ovarian granulosa cell tumor (9 papers, 2010 to 2023). A granulosa-stromal cell tumor that arises from the ovary. "The somatic mutation in the FOXL2 gene c.402C>G (p.Cys134Trp) has recently been identified in the vast majority of adult ovarian granulosa cell tumors (OGCTs) studied." (PMID 20098707, 2010). "Recently, two clinical studies have linked somatic perturbations of FOXL2 with the occurrence of Ovarian Granulosa Cell Tumors (OGCT)." (PMID 20098707, 2010). "Ovarian granulosa cell tumors (GCT) are hormonally-active neoplasms characterized, in the adult-subtype, by a mutation in the FOXL2 gene (C134W)." (PMID 26893359, 2016). "FOXL2 may serve as a immunotherapeutic target for tumor infiltrating lymphocytes in ovarian granulosa cell tumors." (PMID 32814714, 2020). "In addition, genes that are differentially expressed in ovarian granulosa cell tumors (GCTs) are significantly enriched for known FOXL2 target genes, consistent with the prevalence of FOXL2 somatic mutations in these tumors." (PMID 25621074, 2015).
cervical cancer (5 papers, 2015 to 2022). A primary or metastatic malignant neoplasm involving the cervix. "The results from the CCK-8 assays showed that FOXL2 inhibited poGC proliferation in a manner that resembled the role of FOXL2 in human cervical cancer cells." (PMID 32645018, 2020). "As a the new downstream gene of STAT3, our results demonstrated that knockdown of STAT3 or FOXL2 promoted apoptosis and inhibited the growth of cervical cancer cells using RNAi." (PMID 31221094, 2019). "FOXL2 acts as a tumor suppressor in cervical cancer since its overexpression reduces the proliferation of cervical cancer cells." (PMID 30360388, 2018). "Meanwhile, the new pathway has important functions in HeLa cell growth and apoptosis, indicating the new role of FOXL2 in cervical cancer growth, and these results may provide new insight into the crucial transcription factor FOXL2." (PMID 31221094, 2019). "FOXL2 suppresses proliferation, invasion and promotes apoptosis of cervical cancer cells." (PMID 26121593, 2015).
fibroma (5 papers, 2016 to 2023). A non-metastasizing neoplasm arising from the fibrous tissue. "Pure thecoma tumors are very rare, while mixed thecoma-fibromas are much more frequent; thecoma-fibromas, frequently display a variable mixed component of granulosa cells (10–50%): these tumors diplay FOXL2 mutations in about 50% of cases." (PMID 29389895, 2018). "Thus, combination of FOXL2 point mutation analysis and reticulin staining can be employed in differential diagnosis of cellular fibroma and AGCT." (PMID 27770806, 2016). "In addition, no FOXL2 nor DICER1 variant has been identified in fibromas." (PMID 38136408, 2023). "This approach is in line with that of other investigators, who reappraised FOXL2 wild-type AGCT cases, which were previously diagnosed entirely by morphology, as most likely representing thecomas or fibromas." (PMID 35267514, 2022).
Infertility (5 papers, 2018 to 2024). "All showed infertility (76.2% in primary infertility) with an average duration of 5 years (5.17 ± 3.58 yrs), except for one fertile fetus with 3 fetuses positive for maternal FOXL2 mutations (patient #12)." (PMID 35574016, 2022). "Heterozygous mutations in the FOXL2 gene in humans have been linked to premature ovarian insufficiency (POI) and infertility as part of the Blepharophimosis, ptosis, and epicanthus inversus syndrome." (PMID 38517962, 2024). "In a recent study, conditional deletion of Foxl2 in the postnatal uterus resulted in infertility, severely reduced thickness of the stroma layer and a hypertrophic, disorganized appearance of the myometrium." (PMID 29415736, 2018). "Better understanding of the function of FOXL2 in the uterus would possibly suggest novel strategies for treatment of infertility attributed to repeated implantation failure." (PMID 29415736, 2018). "This study further showed that conditional deletion of Foxl2 in the postnatal uterus results in infertility, reduced thickness of the stroma layer and a hypertrophic, disorganized inner myometrial layer." (PMID 29415736, 2018). "We found that the ovarian reserve, quality of oocytes and embryos, and reproductive outcomes were significantly compromised in BPES women positive for FOXL2 mutations compared to those without mutations, although they all presented with infertility." (PMID 35574016, 2022). "BPES is a rare genetic disorder characterized by eyelid manifestation in the presence or absence of infertility or ovary dysfunction, with FOXL2 as the dominant pathogenic gene." (PMID 35574016, 2022). "Ovaries fail to develop properly in FoxL2 knockout mice: the absence of functional granulosa cells in these mutants leads to oocyte atresia and infertility due to progressive follicular depletion." (PMID 35294875, 2022).
ovarian sex cord-stromal tumor (5 papers, 2009 to 2026). A benign or malignant neoplasm that arises from the ovary and is composed of granulosa cells, Sertoli cells, Leydig cells, theca cells, and fibroblasts. "However, molecular alternations are different than those usually observed in ovarian sex cord stromal tumors (e.g., no FOXL2 nor DICER1 variants)." (PMID 38136408, 2023). "Additionally, several studies have confirmed that UTROSCT lacks the characteristic JAZF-1-SUZ12 gene fusion or PHF1 gene rearrangement of endometrial stromal tumors and does not have the FOXL2 and DICER1 gene mutations unique to ovarian sex cord stromal tumors." (PMID 40417005, 2025).
endometriosis (4 papers, 2018 to 2021). The growth of functional endometrial tissue in anatomic sites outside the uterine body. "This prediction requires further investigations although it is consistent with a recent study showing that Foxl2 levels are elevated in the endometrium of patients with endometriosis." (PMID 29415736, 2018). "Indeed, OSC_LEFTY2 did also express FOXL2, which is known to be overexpressed by endometrial cells in endometriosis." (PMID 34238352, 2021). "Of note, Forkhead box L2 (FoxL2), which is expressed in stromal and epithelial endometrial cells, was approximately 3-fold higher expressed in ovarian endometriosis and eutopic endometrium of cases with endometriosis compared to healthy controls, however, no data about the sensitivity was reported." (PMID 33477657, 2021). "Since the infiltration of plasma cells is an indicator of chronic inflammation, and endometriosis is frequently accompanied with chronic inflammation, the presence of chronic inflammation in the background ovary might account for the presence of FOXL2-negative fibroblasts." (PMID 30304016, 2018).
female infertility (4 papers, 2011 to 2024). Diminished or absent ability of a female to achieve conception. "Previous mouse model studies have shown that deletion of SMAD4 and FOXL2 in GnRH results in FSH deficiency and female infertility, and FSH and LH can enhance the activity of the TGF-β/SMAD signaling pathway." (PMID 35326436, 2022). "Ablation of FOXL2 could result in female infertility with follicles blocked between the primordial and primary stages and subsequent follicle atresia." (PMID 35574016, 2022). "In family 1, the absence of female infertility or POF in II:6 suggested that this gene deletion did not affect the ovarian expression of FOXL2, and thus led to BPES type II." (PMID 21321671, 2011).
granulosa cell tumors of the ovary (4 papers, 2018 to 2022). "Recently, a single recurrent somatic mutation in the FOXL2 gene was identified in almost all morphologically adult granulosa cell tumors of the ovary." (PMID 35712094, 2022). "Adult-type granulosa cell tumors of the ovary (aGCTs) are rare gynecologic malignancies that exhibit a high frequency of somatic FOXL2 c.C402G (p.Cys134Trp) mutation." (PMID 29950560, 2018). "But also JAZF1-AS1 has not been associated with ST, thus the connection of the SNP rs849142 and ST remains unknown like mutations in the FOXL2 gene in granulosa cell tumors of the ovary." (PMID 30100989, 2018).
polycystic ovary syndrome (4 papers, 2019 to 2025). A disorder that manifests as multiple cysts on the ovaries. "In polycystic ovary syndrome (PCOS), AMH levels are significantly higher due to an increased number of granulosa cells (GCs) and enhanced transcriptional activity mediated by Foxl2, Sox9, and Gata4." (PMID 40724853, 2025). "A 35-year-old woman with primary infertility, hyperandrogenism, and irregular menses who was previously diagnosed with polycystic ovarian syndrome was diagnosed with AGCT based on histopathological examination and FOXL2 genetic test after laparoscopy." (PMID 33828986, 2021).
adrenal hypoplasia (3 papers, 2011 to 2017). "The roles of forkhead box L2 (Foxl2) and the dosage-sensitive sex reversal-adrenal hypoplasia congenital (AHC) critical region on the X chromosomegene 1 (Dax1) has also been extensively studied during ovarian development." (PMID 28934256, 2017).
breast carcinoma (3 papers, 2017 to 2020). "With the goal of validating the immunogenicity and effectiveness of FOXL2-targeted response, we developed a plasmid-DNA vaccine encoding murine Foxl2 that was able to reduce tumor progression in FOXL2-expressing ovarian and breast cancer models in a T cell–mediated manner." (PMID 32814714, 2020). "FoxL2-TT immunization suppresses tumor growth in FOXL2-expressing ovarian and breast cancer models." (PMID 32814714, 2020). "In aggressive breast cancers, the expression levels of positive regulators of SERPINB2, such as FOXL2 (Z-score = 2.863, p-value = 0.258) and ERK (Z-score = 3.346, p-value = 0.677), were activated." (PMID 30965654, 2019).
colorectal cancer (3 papers, 2010 to 2018). A primary or metastatic malignant neoplasm that affects the colon or rectum. "We have sequenced the FOXL2 open reading frame in a panel of tumor cell lines (NCI-60, colorectal carcinoma cell lines, JEG-3, and KGN cells)." (PMID 20098707, 2010). "Other researchers had also pointed out that some stromal cells of ovarian metastases from colorectal cancer have alpha-inhibin, another ovarian stroma marker, not as specific or sensitive as FOXL2, and SF-1." (PMID 30304016, 2018).